RAD21 (RAD21 cohesin complex component)
Diseases named in the same sentence as RAD21 in open-access papers (continued):
Sharing a sentence is not in itself a finding about the gene and the disease.
lymphoma (2 papers, 2014 to 2022). A malignant (clonal) proliferation of B- lymphocytes or T- lymphocytes which involves the lymph nodes, bone marrow and/or extranodal sites. "Here, we present the discovery of a recurrent heterozygous RAD21 germline aberration at amino acid position 298 (p.P298S/A) identified in three children with lymphoblastic leukemia or lymphoma in a total dataset of 482 pediatric cancer patients." (PMID 35563565, 2022). "Our clinical and functional data therefore suggest that RAD21 germline variants can predispose to childhood lymphoblastic leukemia or lymphoma without displaying a CdLS phenotype." (PMID 35563565, 2022). "Previous work in lymphoma cells had indicated that cohesin components, including Rad21, but not CTCF, repress KSHV immediate-early gene expression." (PMID 24415941, 2014).
male infertility (2 papers, 2024 to 2025). The inability of the male to effect fertilization of an ovum after a specified period of unprotected intercourse. "Collectively, these results highlight a critical role of YAP1 in determining the fate determinations of human SSCs and male infertility through the YAP1/RAD21/NEDD4 pathway." (PMID 39659446, 2024). "Collectively, we are the first to demonstrate that the YAP1/RAD21/NEDD4 pathway mediates the fate determinations of human SSCs and abnormality or mutations of YAP1 are associated with male infertility." (PMID 39659446, 2024).
ovarian tumors (2 papers, 2013 to 2024). "When analyzing ovarian tumors according to the number of Rad21 CNV (0–4 low and 4–20 high), we observed that the number of Rad21 copies is related to a worse prognosis in this type of cancer." (PMID 39408764, 2024).
adrenocortical carcinoma (1 paper, 2022). "The association of high RAD21 expression with lower survival was also observed in multiple cancer types, including adrenocortical carcinoma, bladder urothelial carcinoma, cervical squamous cell carcinoma, lung squamous cell carcinoma, mesothelioma, and sarcoma." (PMID 36201246, 2022).
Anxiety (1 paper, 2020). Intense feelings of nervousness, tension, or panic often arise in response to interpersonal stresses. "14/25 RAD21 patients (56%) with sufficiently available information on behavior had problems, mainly features of anxiety, ADHD, ASD, and obsessive–compulsive behavior." (PMID 32193685, 2020).
atopic asthma (1 paper, 2015). An asthma that is characterized by symptoms that are triggered by an allergic reaction caused by inhaled allergens such as dust mite allergen, pet dander, pollen and mold. "SMC3 and RAD21 interact with MXI1 (found among ChIP targets with decreased mRNA) to function in the cohesin complex, and the former is associated with atopic asthma." (PMID 26544975, 2015).
autism (1 paper, 2020). Persistent deficits in social interaction and communication and interaction as well as a markedly restricted repertoire of activity and interest as well as repetitive patterns of behavior. "Still, all data point to a lower prevalence and decreased severity of ID in RAD21 patients compared to NIPBL and SMC1A groups: developmental milestones are more frequently attained, the cognitive level is estimated higher, and aggression and autism are less frequent." (PMID 32193685, 2020).
autonomic dysfunctions (1 paper, 2020). "CdLS characteristics such as sleep disturbances and autonomic dysfunctions in individuals with RAD21 variants are still largely unknown." (PMID 32193685, 2020).
Azoospermia (1 paper, 2025). Absence of any measurable level of sperm,whereby spermatozoa cannot be observed even after centrifugation of the semen pellet. "Abnormalities in the molecular pathway synergistically regulated by RAD21 and YAP1 can directly lead to impaired spermatogenesis, which provides a new direction in the mechanistic resolution of non-obstructive azoospermia." (PMID 40642059, 2025).
chronic intestinal pseudo‐obstruction (1 paper, 2025). "Here, we discuss the evidence for DNA repair defects in enteric neuropathies, most notably, the reported relationship between inherited mutations in RAD21 and LIG3 with chronic intestinal pseudo‐obstruction and mitochondrial gastrointestinal encephalomyopathy disorders, respectively." (PMID 39004995, 2025).
congenital heart disease (1 paper, 2020). A heart disease that is present at birth. "It is possible that RAD21 defect might be responsible for this patient’s congenital heart disease." (PMID 32296131, 2020).
cornea diseases (1 paper, 2019). "Rad21 has been found to be highly expressed in both postnatal developing cornea and adult cornea in mice compared with another ocular tissue, suggesting potential roles of Rad21 in cornea development and cornea diseases." (PMID 31781308, 2019).
cyst (1 paper, 2024). A sac-like closed membranous structure that may be empty or contain fluid or amorphous material. "RAD21, SMC3, and MEI2 are linked to bloom-promoting sex, HOP2 and MSH4 to cyst germination, while SPO11, MND1, and DMC1 are common to both cyst-forming and non-encysting sex." (PMID 39367346, 2024).
endothelial dysfunction (1 paper, 2010). In vascular diseases, endothelial dysfunction is a systemic pathological state of the endothelium (the inner lining of blood vessels) and can be broadly defined as an imbalance between vasodilating and vasoconstricting substances produced by (or acting on) the endothelium. "Nevertheless, these data provide strong evidence that the crypt death in Rad21+/− mice is unlikely to be a consequence of toxicity secondary to endothelial dysfunction." (PMID 20711430, 2010).
erythroderma (1 paper, 2025). "In this case, the clinical features of patient with CdLS phenotype correlated with RAD21 gene alterations, while TNFAIP3 modifications were consistent with her history of erythematous, scaly, and pruritic plaques, culminating in erythroderma." (PMID 41226818, 2025).
esophageal squamous cell carcinoma (1 paper, 2022). Esophageal squamous cell carcinoma (ESCC) is a type of esophageal carcinoma (EC) that can affect any part of the esophagus, but is usually located in the upper or middle third. "In contrast, high RAD21 expression was significantly correlated with better OS in esophageal squamous cell carcinoma (ESCC)." (PMID 35371307, 2022).
familial cancer (1 paper, 2012). "RAD21 expression in familial cancers is reflected by expression changes in copy-number expression." (PMID 22537934, 2012). "Similarly, in our cohort of familial cancers receiving adjuvant chemotherapy, RAD21 expression correlated with a poorer prognosis." (PMID 22537934, 2012).
Gastro-esophageal reflux (1 paper, 2020). "Gastro-esophageal reflux is similar in frequency but in RAD21 it is typically mild and restricted to early childhood." (PMID 32193685, 2020).
glioma (1 paper, 2022). A benign or malignant brain and spinal cord tumor that arises from glial cells (astrocytes, oligodendrocytes, ependymal cells). "Another study performed in low-grade gliomas reported a consistent signature in the methylation of MGMT, MLH3, RAD21, and SMC4 promoter region predictive value for response to temozolomide." (PMID 35359376, 2022).
Hirsutism (1 paper, 2020). Abnormally increased hair growth referring to a male pattern of body hair (androgenic hair). "RAD21 patients less frequently have increased body hair (hirsutism, bushy eyebrows, low scalp hair lines), major limb malformations are not reported, and hands and feet are generally of normal size." (PMID 32193685, 2020).
hydatidiform mole (1 paper, 2023). A gestational trophoblastic disorder characterized by marked enlargement of the chorionic villi, hyperplasia of the villous trophoblastic cells and hydropic changes. "We performed chromatin immunoprecipitation (ChIP) for cohesin subunits RAD21, SA1 and SA2 in hTERT CHM13 (complete hydatidiform mole) and hTERT RPE-1 (retinoid pigmented epithelium) cell lines." (PMID 38040722, 2023).
inflammatory skin disease (1 paper, 2025). Inflammatory skin disorders covers a broad category that includes many conditions ranging in severity, from mild itching to grave medical health complications These disorders are common in people of all ages and races. "CdLS is a rare disorder due to heterozygous mutations in cohesin complex genes like RAD21, affecting developmental pathways and typically not overlapping with inflammatory skin diseases." (PMID 41226818, 2025). "Thus, the combined effect of impaired transcriptional regulation (i.e., a mutation in RAD21) and enhanced inflammatory signaling (i.e., a mutation in TNFAIP3) may explain the coexistence of developmental abnormalities (CdLS) and inflammatory skin disease (pustular psoriasis) in the same patient." (PMID 41226818, 2025).
intestinal pseudo-obstruction (1 paper, 2025). A type of ILEUS, a functional not mechanical obstruction of the INTESTINES. "Interestingly, a recently described syndrome of intestinal pseudo‐obstruction associated with a dominant mutation in RAD21—a cohesin complex member—also hints at a noncanonical role of cohesins." (PMID 41245052, 2025).
KBG syndrome (1 paper, 2020). KBG syndrome is a rare condition characterized by a typical facial dysmorphism, macrodontia of the upper central incisors, skeletal (mainly costovertebral) anomalies and developmental delay. "We found that KBG syndrome was the second diagnosis for individuals harbouring causative variants in NIPBL and RAD21 genes." (PMID 32033219, 2020). "Whereas for NIPBL and RAD21 patients, KBG syndrome was the second most common diagnosis (top-five rank), 54.5% (18/33) and 66,7% (2/3), Rubinstein–Taybi syndrome appeared most frequently in SMC1A and HDAC8 patients, 50.0% (4/8) and 80.0% (4/5), respectively." (PMID 32033219, 2020).
kidney cancer (1 paper, 2019). Primary or metastatic malignant neoplasm involving the kidney. "ARNT, CTCF, POLR2A, RAD21 and REST were downregulated in kidney cancer samples and indicated poor prognosis when lowly expressed, which revealed that ARNT, CTCF, POLR2A, RAD21 and REST tended to be risk factors with lower gene expression." (PMID 31727869, 2019).
liver cirrhosis (1 paper, 2022). "Some of the important hub genes in the BisoGenet-derived PPI for liver cirrhosis and HCC diseases were E2F1, TAL1, CEBPB, ELF1, RAD21, CEBPB, and MYC." (PMID 35265561, 2022).
liver neoplasm (1 paper, 2025). Tumors or cancers of the LIVER. "The ‘liver neoplasms’ CTD over-representation could be attributed to cell cycle-related pathway enrichment and corresponding genes (cell cycle: PDS5A, ORC6, RAD21, ZBTB17; Thyroid cancer: CTNNB1, RET) identified from our CRIPSR screens." (PMID 41446233, 2025).
metastatic prostate carcinoma (1 paper, 2024). A carcinoma that arises from the prostate gland and has spread to other anatomic sites.
microcephaly (1 paper, 2020). A congenital or acquired developmental disorder in which the circumference of the head is smaller than normal for the person's age and sex. "Patients with RAD21 variants have generally less impaired growth at birth, and short stature and microcephaly develop postnatally." (PMID 32193685, 2020).
Mungan syndrome (1 paper, 2020). "RAD21 variants have also been associated with sclerocornea and Mungan syndrome (Chronic Idiopatic Intestinal Pseudoobstruction; OMIM #611376, in patients with biallelic RAD21 variants), each in a single family in which no remarks on CdLS features were made in the report." (PMID 32193685, 2020).
orchitis (1 paper, 2021). Inflammation of one or both testes due to viral or bacterial infections. "On the other hand, Klf2, Klf4, Nfe2l2/Nrf2, Id1, Id2, Rad21, Xrcc1, and Cycs were found to be negatively correlated with androgen synthesis during orchitis." (PMID 35111154, 2021).
osteoporosis (1 paper, 2016). A condition of reduced bone mass, with decreased cortical thickness and a decrease in the number and size of the trabeculae of cancellous bone (but normal chemical composition), resulting in increased fracture incidence. "For the TFBSs, we identified 2 TFBSs (EZH2 and RAD21) for enrichment, and 2 TFBSs (ELK4 and HDAC1) for depletion in the promoters of osteoporosis-associated genes, respectively." (PMID 27465306, 2016).
ovarian endometrioid carcinoma (1 paper, 2022). "RAD21 showed the highest high-positive rate in ovarian endometrioid carcinoma (78.57%) and the lowest high-positive rate in ovarian mucinous carcinoma (57.14%)." (PMID 35860572, 2022).
promyelocytic leukemia (1 paper, 2025). "Interestingly, RAD21, a cohesion involved in ALT-associated promyelocytic leukemia body, and RECQL4, a helicase involved in telomeric integrity maintenance, are often amplified in ALT cell lines." (PMID 40725011, 2025).
pustular psoriasis (1 paper, 2025). "Histopathology confirmed pustular psoriasis, and clinical exome sequencing identified a heterozygous likely pathogenic variant in RAD21, associated with CdLS type 4 (CdLS4), and a heterozygous variant of uncertain significance in TNFAIP3, which is linked to familial autoinflammatory syndrome." (PMID 41226818, 2025).
situ carcinomas (1 paper, 2011). "RAD21 immunohistochemistry was performed on 345 invasive and 60 pure in situ carcinomas." (PMID 21255398, 2011).
skin cutaneous melanoma (1 paper, 2022). "The results demonstrated that RAD21 was amplified and overexpressed in various human tumors, including OV and skin cutaneous melanoma (SKCM)." (PMID 36201246, 2022).
small cell lung carcinoma (1 paper, 2022). Small cell lung cancer (SCLC) is a highly aggressive malignant neoplasm, accounting for 10-15% of lung cancer cases, characterized byrapid growth, and early metastasis. "The KEGG pathway analysis revealed that the most significantly altered pathways in the RAD21 high expression group were cell cycle and small cell lung cancer (P-adjusted < 0.05)." (PMID 35371307, 2022).
squamous cell carcinoma (1 paper, 2018). A carcinoma arising from squamous epithelial cells. "Yamamoto et al4 found that Rad21 is closely related to invasion and metastasis of squamous cell carcinoma of the oral cavity." (PMID 29797792, 2018). "After excluding 4 cases with Rad21 mutations and patients with a lack of follow‐up data or without valid data, 236 patients with squamous cell carcinoma entered the overall survive (OS) analysis, and 207 patients for disease‐free survive (DFS)." (PMID 29797792, 2018).
trisomy 8 (1 paper, 2024). "The elevated frequencies of both RAD21 gene promoter methylation and ASXL1 mutations in patients with trisomy 8 compared to other cytogenetic groups, along with the fact that RAD21 gene is located on chromosome 8, lay the groundwork for further research into this specific cytogenetic group." (PMID 39459611, 2024).
cancer (86 papers, 2010 to 2026). A tumor composed of atypical neoplastic, often pleomorphic cells that invade other tissues. "In the KEGG pathway enrichment analysis data demonstrated that; homologous recombination, ERBB signaling pathway, cell cycle, PI3K-Akt signaling pathway, microRNAs in cancer and pathways in cancer were associated with RAD21, RAD50 and BARD1." (PMID 37474724, 2023). "Although the correlation between RAD21 expression and cancer risk is relatively well established, little is known regarding the causes and consequences of RAD21 over-expression in tumorigenesis." (PMID 37381036, 2023). "The core complex subunits SMC1A, SMC3, STAG1/2, and RAD21 as well as its modulators, have been found to be recurrently mutated in human cancers." (PMID 35287703, 2022). "As a protein that plays an important role in DSB repair, RAD21 has been reported to be associated with cancer therapy resistance." (PMID 35860572, 2022). "Here, we describe a recurrent and functionally relevant mutated position within RAD21 in three children with lymphatic malignancies originating from three different independent cancer cohorts." (PMID 35563565, 2022). "This work demonstrates that the association of RAD21 with these 7 co-regulated genes is likely to be functionally important, and has potential for disruption in pathologies such as cancer." (PMID 35906355, 2022). "Cohesin is among the most commonly mutated protein complexes in cancer, and somatic mutations and amplification of RAD21 have been reported in human tumours." (PMID 34846284, 2021). "A specific issue that needs attention is the risk to develop cancer (incidentally reported to date in RAD21 patients)." (PMID 32193685, 2020). "Small intestine crypt cells with rapid cell proliferation such as malignant tumors in Rad21+/− mutant animals are more susceptible to killing by radiation." (PMID 29797792, 2018). "Consistently, our model indicating that RAD21 as the core subunit of cohesin may influence cancer-associated gene expression partial due to chromatin excessive extrusion." (PMID 37381036, 2023). "Thus, our results identified an association between alterations in RAD21 and high telomeric content pan-cancer, as well as in specific disease groups, in both the FMI and PCAWG datasets." (PMID 35227290, 2022). "Finally, querying the COSMIC database, 871 of 63,847 (1.4%) cancer samples tested harbored somatic mutations in the RAD21 coding region." (PMID 35287703, 2022). "The enrichment for LoF-intolerance amongst the RAD21 co-regulated genes could be associated with an importance of these genes to normal development and cancer." (PMID 35906355, 2022). "In addition, aberrant function of RAD21 has been implicated in multiple cancer types, including breast cancer, colon cancer, and myeloid leukemia, and is correlated with malignant progression and poor prognosis." (PMID 36201246, 2022). "Furthermore, as with other RAD21 missense variants in cancer, the here identified RAD21 p.P298S/A alterations are heterozygous and mutually exclusive to other variants in cohesin complex genes." (PMID 35563565, 2022). "PPI analysis illustrated that STAG2 and RAD21 could cross-talk through cancer-associated modules and performed the core roles of the whole PPI network." (PMID 35371307, 2022). "Somatic mutations and changes in expression of RAD21 are common in many types of cancer." (PMID 35906355, 2022). "While cancer-associated mutations in genes encoding RAD21, SMC3, and STAG1 are always heterozygous, mutations in the X chromosome-located genes SMC1A and STAG2 can result in complete loss of function due to hemizygosity (males), or silencing of the wild type during X-inactivation (females)." (PMID 33284104, 2020). "In addition, mutations in genomic binding sites of CTCF/cohesin or changes in cohesin protein levels (RAD21) have been associated to cancers." (PMID 30873408, 2019).